IL37 (interleukin 37)
Diseases named in the same sentence as IL37 in open-access papers (continued):
Sharing a sentence is not in itself a finding about the gene and the disease.
Lymphadenopathy (3 papers, 2018 to 2021). Enlargement (swelling) of a lymph node. "In addition, more diverse clinical features (fever, sore throat, rash, lymphadenopathy, splenomegaly, myalgia, and arthralgia) were significantly related to higher levels of IL-37." (PMID 33652679, 2021). "Moreover, serum IL-37 levels correlated significantly with clinical features of fever, skin rash, lymphadenopathy, splenomegaly, myalgia, and arthralgia in patients with AOSD." (PMID 29566725, 2018). "Moreover, the patients who had sore throat, lymphadenopathy, splenomegaly, myalgia, and arthralgia had a higher level of IL-37 than those who did not have these symptoms." (PMID 29566725, 2018).
myocarditis (3 papers, 2017 to 2022). Myocarditis is a condition that is characterized by inflammation of the heart muscle (myocardium). "In view of the strong association between IL-37 and NLRP3, we further investigated the effect of IL-37 on NLRP3 inflammasome in CVB3-induced myocarditis." (PMID 36418383, 2022). "In this study, we found that IL-37 significantly ameliorated the signs of myocarditis and existed as a suppressor of NLRP3 inflammasome in a mouse VMC model." (PMID 36418383, 2022). "We found in this study that the levels of GSDMD protein were markedly decreased in VMC with IL-37 treatment compared with the VMC group (P < 0.001), which implied that IL-37 inhibits pyroptosis in CVB3-induced myocarditis." (PMID 36418383, 2022). "Our current research aims to further explore the mechanism by which IL-37 affects VMC, so as to provide a new therapeutic option for the treatment of CVB3-induced myocarditis." (PMID 36418383, 2022).
oral squamous cell carcinoma (3 papers, 2016 to 2022). "For instance, in Oral Squamous Cell carcinoma (OSCC), IL-37 inhibited the proinflammatory effects of IL-18 and the increased IL-18/IL-37 ratio in serum predicted shorter overall and disease-free survival." (PMID 35211118, 2022). "The expression of IL-37 increased from normal control (NC) to Oral leukoplakia (OLK) and oral squamous cell carcinoma (OSCC)." (PMID 27225603, 2016).
osteoporosis (3 papers, 2015 to 2022). A condition of reduced bone mass, with decreased cortical thickness and a decrease in the number and size of the trabeculae of cancellous bone (but normal chemical composition), resulting in increased fracture incidence. "IL-37 is an anti-inflammatory cytokine; unexpectedly, significantly increased IL-37 levels were in patients with RA and osteopenia or osteoporosis." (PMID 35955873, 2022). "Strikingly, serum IL-37 levels were higher in AS patients with osteoporosis than those without." (PMID 25627863, 2015). "Interestingly, the expressions of IL-37 mRNA in PBMCs and the levels of serum IL-37 were significantly higher in patients with osteoporosis compared with patients without osteoporosis." (PMID 25627863, 2015).
ovarian carcinoma (3 papers, 2016 to 2025). A malignant neoplasm originating from the surface ovarian epithelium. "However, high levels of IL-37 in the serum of patients with certain cancers such as ovarian cancer were found to be associated with poor prognosis, poor overall survival and progression-free survival, while the connection of IL-37 with PCa is unclear yet." (PMID 36237303, 2022).
pancreatitis (3 papers, 2020 to 2025). Inflammation of the pancreas. "The results showed that phosphorylated STAT3 increased in the pancreatitis condition and that this increase was rectified by IL-37." (PMID 36166295, 2022). "There appears to be a biphasic response to dosing of IL-37 in CAE-induced pancreatitis." (PMID 36166295, 2022). "Moreover, we performed Western blotting and histochemistry analysis; expression of pyroptosis-related proteins was upregulated in the pancreatitis condition and significantly downregulated by IL-37." (PMID 36166295, 2022). "Emerging evidence underscores the pivotal role of interleukins (ILs) in pancreatitis pathogenesis across the disease spectrum, encompassing both pro-inflammatory mediators (e.g., IL-1β, IL-6, and IL-8) and anti-inflammatory regulators (e.g., IL-10 and IL-37) 24-26." (PMID 41208897, 2025).
pulmonary tuberculosis (3 papers, 2017 to 2020). A bacterial infection that affects the lungs and is caused by Mycobacterium tuberculosis. "This work aims to assess the level of expression of IL-18, IL-18BP, IL-18R, as well as IFN-γand IL-37 genes in patients with active pulmonary tuberculosis (ATB), healthy individuals with latent M.tb infection (LTB), and healthy uninfected controls (Control)." (PMID 32521630, 2020). "Allelic distribution and frequencies of IL-37 in pulmonary tuberculosis patients and controls." (PMID 28076390, 2017). "Frequencies of IL-37 genotype in pulmonary tuberculosis patients and controls." (PMID 28076390, 2017). "Therefore, direct analysis of serum components of the IL-18/IL-37 signalling complex and IP-10 may be applicable in designing novel rapid screening tests for pulmonary TB." (PMID 31821340, 2019). "In our earlier studies, the serum concentration of the IL-37 protein was similar in the group of patients with active pulmonary TB and healthy individuals with or without latent M.tb infection." (PMID 32521630, 2020). "We performed a combined analysis of the proteins, free and total IL-18, IL-18BP, IL-37, IFN-γ in QFT supernatants and directly in serum samples from pulmonary TB patients and healthy individuals with or without latent M. tb infection to identify new markers for the diagnosis of ATB." (PMID 31821340, 2019).
Sjögren syndrome (3 papers, 2020 to 2025). "The pro-form of IL-37 is activated via cleavage by caspase-1, an enzyme that is also found to be overexpressed in the early stages of Sjögren’s syndrome and whose levels correlate with increased apoptosis in epithelial cells." (PMID 40430016, 2025). "This study aims to explore the contribution of the IL-37/IL-18/IL-18BP/IL-18R signaling axis to the immunopathogenesis of primary Sjögren’s syndrome, with a focus on its local and systemic expression profiles." (PMID 40430016, 2025). "The objective of this study was to explore the expression profile of the Interleukin (IL)-37/IL-18/IL-18BP/IL-18R axis in patients with primary Sjögren’s syndrome (pSS)." (PMID 40430016, 2025). "The IL-18/IL-37/IL-18BPa/IL-18Rα axis, via the induction of IFN-γ, appears to play a central role in the pathogenesis of Sjögren’s syndrome." (PMID 40430016, 2025). "However, to date, the expression and role of IL-37 have not been studied in the context of Sjögren’s syndrome." (PMID 40430016, 2025).
skin inflammation (3 papers, 2021 to 2025). "Overall, the results of these studies suggest rather beneficial anti-inflammatory effects of IL-37 in mouse models of skin inflammation." (PMID 33796114, 2021). "Taken together, these observations suggest that IL-37 expression is generally reduced during skin inflammation in vivo." (PMID 33796114, 2021). "In summary, in healthy individuals, IL-37 is expressed mainly in the skin, where keratinocytes are the major producing cell type, and IL-37 expression is generally reduced during skin inflammation." (PMID 33796114, 2021). "Only few studies have addressed potential effects of IL-37 in the context of human skin inflammation, but their results concur to suggest anti-inflammatory activity of this cytokine." (PMID 33796114, 2021). "This review summarized the up-to-date literature and the importance of the anti-inflammatory functions of the four IL-1 family cytokines IL-1Ra, IL-36Ra, IL-37, and IL-38 in skin inflammation." (PMID 33796114, 2021). "Cultured primary human keratinocytes express predominantly IL-37b and IL-37 expression levels markedly increased with cell differentiation in vitro, suggesting that the downregulation of IL-37 expression during skin inflammation in vivo may be related to keratinocyte de-differentiation." (PMID 33796114, 2021). "Transcriptomic analysis and machine-learning models enable patient stratification, allowing for the identification of biomarkers such as ADAM8, CD47, BATF, SELE, IL-37 that may aid in diagnosis and differentiating ACD from other forms of dermatitis." (PMID 40181807, 2025).
Splenomegaly (3 papers, 2018 to 2021). Abnormal increased size of the spleen. "In murine studies, we demonstrate that aging‐associated increases in chronic inflammation, the onset of splenomegaly, and the accumulation of myeloid populations in the bone marrow and spleen can be prevented by the anti‐inflammatory cytokine IL‐37." (PMID 33480151, 2021). "Furthermore, we demonstrate for the first time, to our knowledge, that treating aged mice with recombinant IL‐37 abrogates aging‐associated splenomegaly." (PMID 33480151, 2021). "Furthermore, we demonstrate that transgenic expression of interleukin‐37 (IL‐37) in aged mice reduces or prevents aging‐associated chronic inflammation, splenomegaly, and accumulation of myeloid cells (macrophages and dendritic cells) in the bone marrow and spleen." (PMID 33480151, 2021). "In addition to abrogating aging‐associated chronic inflammation, we found that transgenic expression of IL‐37 also significantly reduced splenomegaly in aged mice." (PMID 33480151, 2021). "The expression levels of IL-37 were closely related to the patients with AOSD who also had fever, skin rash, lymphadenopathy, splenomegaly, myalgia, and arthralgia." (PMID 29566725, 2018).
synovitis (3 papers, 2019 to 2024). Inflammation of a synovial membrane. "Transfection of synovial cells with IL-37-expressing lentivirus resulted in relief not only of synovitis but also of the cartilage damage and inflammation caused by synovitis." (PMID 38053836, 2023). "IL‐37 was highly expressed in synovial fluid of patients with synovitis than in those with OA and disc displacement and was closely related to visual analogue scale (VAS) score." (PMID 31560411, 2019). "In the synovial fluid, IL‐37 was highly expressed in active inflammation in patients with synovitis than in those with OA and DDWoR." (PMID 31560411, 2019). "This further confirms our speculation that low intracellular of IL-37 may be responsible for the development of synovitis in senescent synoviocytes, which is detrimental to both the development and progression of TMJOA." (PMID 38053836, 2023). "After elaborating on the mechanism of intracellular IL-37 maturation and nuclear translocation, we explore whether intracellular IL-37 is effective against synovitis." (PMID 38053836, 2023). "In a synovitis cell model constructed using IL-1β, HMGB1, and LPS, intracellular IL-37 was responsively upregulated (more pronounced with stimulation of IL-1β)." (PMID 38053836, 2023).
uveitis (3 papers, 2011 to 2022). An inflammatory process affecting a part of or the entire uvea. "The fact that only an association was found with ocular BD and not with VKH uveitis suggests that our finding cannot be generalized for all uveitis entities and that further research is necessary to study the association of IL-37 with other uveitis types." (PMID 27775096, 2016).
abdominal aortic aneurysm (2 papers, 2022). Enlargement and ballooning of the vessel that supplies arterial blood to the abdomen, pelvis and legs. "However, the role of IL-37 in patients with abdominal aortic aneurysm (AAA), another artery disease, is yet to be elucidated." (PMID 35602104, 2022).
adenoma (2 papers, 2019 to 2022). A neoplasm arising from the epithelium. "In biopsies of the distal colon without adenomas and carcinomas, there was a lower level of gene expression of Rorγt and higher gene expression of Foxp3 in IL-10KO/IL-37tg mice indicating a tumor protective immune status associated with transgene IL-37 expression." (PMID 31781119, 2019).
AIDS (2 papers, 2019 to 2020). A syndrome resulting from the acquired deficiency of cellular immunity caused by the human immunodeficiency virus (HIV). "The IL-1 cytokine family (IL-1α, IL-1β, IL-1Ra, IL-18, IL-36Ra, IL-36α, IL-37, IL-36β, IL-36g, IL-38, IL-33) was defined to be principally responsible for the inflammatory nature of polygenic AIDs." (PMID 33708123, 2020). "Thus, the absence of the IL37 gene in chimpanzees is likely not related to their better resistance (compared to humans) to developing lentivirus-related AIDS." (PMID 31138840, 2019).
angina (2 papers, 2017 to 2022). "Plasma interleukin-37 levels were measured in 41 patients with ST elevation myocardial infarction (STEMI), 41 patients with non-STEMI, 42 patients with unstable angina, and 40 controls." (PMID 28039466, 2017).
autism spectrum disorder (2 papers, 2021 to 2025). A spectrum of developmental disorders that includes autism, and Asperger syndrome. "The observation of IL-38 and IL-37 deficiency in brain tissue from individuals with autism, along with their significant anti-inflammatory effects, suggests that these cytokines may serve as viable therapeutic targets for autism spectrum disorder." (PMID 41425587, 2025). "The characterization of IL-38 and of IL-37 in autism spectrum disorder indicate an important progression in our comprehension of the neuroinflammatory processes that underlie this complex neurodevelopmental illness." (PMID 41425587, 2025). "Expression patterns of IL-37 and IL-38 in autism spectrum disorder (ASD)." (PMID 41425587, 2025). "This review aims to comprehensively examine the current knowledge of the functions of IL-38 and IL-37 in autism spectrum disorder, integrating recent research findings to clarify their potential mechanisms of action, diagnostic significance, and treatment implications." (PMID 41425587, 2025). "This study utilized post-mortem brain samples from the University of Maryland NeuroBioBank to evaluate the gene expression of IL-38 and IL-37 in the amygdala of children with a confirmed diagnosis of autism spectrum disorder (ASD) against eight age-matched non-ASD controls." (PMID 41425587, 2025).
bacteremia (2 papers, 2021). "Novel anti-inflammatory cytokines, such as IL-37 and IL-38, have recently been characterized and shown to reduce inflammation in mice with bacterial sepsis." (PMID 34988552, 2021).
dengue (2 papers, 2023). "Research into IL-37's sources, changes, and clinical implications in dengue patients will be beneficial to our understanding of the disease." (PMID 37024713, 2023). "Whether IL-37 has a regulatory effect on CRP levels in dengue patient needs to be further investigated." (PMID 37024713, 2023). "To date, there are few studies reporting correlations between dengue fever (DF) and IL-37." (PMID 37024713, 2023).
disseminated candidiasis (2 papers, 2014 to 2021). Systemic candidiasis occurs when Candida yeast enters the bloodstream and may spread (becoming disseminated candidiasis) to other organs, including the central nervous system, kidneys, liver, bones, muscles, joints, spleen, or eyes. "We conclude that IL-37 interferes with the innate protective anti-Candida host response by reducing the production of proinflammatory cytokines and suppressing neutrophil recruitment in response to Candida, resulting in an increased susceptibility to disseminated candidiasis." (PMID 25620965, 2014). "On the one hand, administration of IL-37 in vivo reduces host pro-inflammatory responses and survival to disseminated candidiasis, thereby abolishing the protective effects of TI." (PMID 34248996, 2021). "We assessed the role of IL-37 in a murine model of disseminated candidiasis using mice transgenic for human IL-37 (hIL-37Tg)." (PMID 25620965, 2014). "In the present study, we demonstrate that overexpression of IL-37 is detrimental for the early host defense against C. albicans in a murine model of disseminated candidiasis." (PMID 25620965, 2014). "Since in models of live infection blocking inflammation mediated by cytokines such as IL-1 or TNFα can be either detrimental or beneficial for the outcome of the host, we therefore carried-out studies of disseminated candidiasis in mice expressing human IL-37." (PMID 25620965, 2014). "In conclusion, overexpression of IL-37 is not conducive to the early host defense against C. albicans in a murine model of disseminated candidiasis, so the timing of IL-37 expression in the inflamed tissue sites is vital for controlling inflammation in the host." (PMID 34248996, 2021).
Erythema (2 papers, 2024). Redness of the skin, caused by hyperemia of the capillaries in the lower layers of the skin. "Our primary outcomes comprised the clinical symptom and TCM syndrome scores, and the scores of Dermatology Life Quality Index, erythema index, and IL-37 levels." (PMID 39175550, 2024). "The study assessed the effects of various concentrations of dapagliflozin ointment on levels of tumor necrosis factor-alpha (TNF-alpha), interleukin-8 (IL-8), IL-17, and IL-37, as well as on erythema, scaling, and epidermal thickness." (PMID 39044933, 2024).
fibromyalgia (2 papers, 2019). A chronic disorder of unknown etiology characterized by pain, stiffness, and tenderness in the muscles of neck, shoulders, back, hips, arms, and legs. "Similarly, IL-37 also exerts inhibitory effect on inflammation of fibromyalgia." (PMID 30728750, 2019). "At the same time, IL-37 could inhibit the inflammation response of IL-1 family members and TNF in fibromyalgia." (PMID 30728750, 2019). "Previous studies have showed that IL-37 is also involved in the improvement of inflammation due to mast cell activation induced by fungi and the inhibition of proinflammatory IL-1 family members and TNF by this inhibitory cytokine in fibromyalgia could have a therapeutic effect." (PMID 31686988, 2019).
hyperlipidemia (2 papers, 2015 to 2020). "The protective effect of IL-37 for hyperlipidemia has been observed in mice (IL-37-Tg) fed a high-fat diet, which, after 16 weeks of intervention, showed reduced plasma cholesterol levels and decreased free fatty acids and triglycerides compared to wild controls." (PMID 33028050, 2020).
leprosy (2 papers, 2018 to 2024). Leprosy is a chronic infectious disease affecting primarily the skin and peripheral nervous system. "When compared to control tissues, lepromatous leprosy revealed greater IL-37 expression levels in macrophages in contrast to the tuberculoid form where elevations in IL-37 expression were confined predominantly to lymphocytes." (PMID 29641433, 2018).
leukocytosis (2 papers, 2015 to 2021). "The expression level of IL-37 was related to leukocytosis while IL-18 was related to pleuritis, pneumonitis, abnormal LFT, and hyperferritinemia." (PMID 33652679, 2021). "In contrast, serum IL-37 level was only higher in patients with leukocytosis (p < 0.01)." (PMID 33652679, 2021).
liver cirrhosis (2 papers, 2019 to 2021). "The correlation of serum IL-37 with disease severity of liver cirrhosis in humans indicates the clinical relevance of our experimental findings." (PMID 33746950, 2021). "In a large clinical cohort, we observed a positive correlation of serum IL-37 levels with disease severity in liver cirrhosis." (PMID 33746950, 2021). "In addition, we demonstrate the correlation of IL-37 serum levels with disease severity in human liver cirrhosis." (PMID 33746950, 2021). "Interestingly, IL-37 serum levels are also higher in patients with liver cirrhosis correlating with the CP- and MELD score as well as platelet counts and hemoglobin levels." (PMID 33746950, 2021).
lung aspergillosis (2 papers, 2014 to 2019). "In addition, the intraperitoneal injection of IL-37 significantly decreases the expression of NLRP3 in the mouse lung aspergillosis model." (PMID 31736917, 2019).
lung diseases (2 papers, 2019 to 2022). "In regards to such a supposition, the co-expression of the proteins of the IL-18/IL37 signalling complex and IP-10 should be further analysed in patients with pulmonary disease including those with pulmonary disease other than TB." (PMID 31821340, 2019).